BCL2L13 (BCL2 like 13)
Description:
May promote the activation of caspase-3 and apoptosis.
Synonyms: Bcl2-L-13; MIL1; BCL-RAMBO
Tractability: Antibody: UniProt predicts a signal peptide or a membrane-spanning region. PROTAC: ubiquitination databases record sites on it; its protein half-life has been measured.
Target class: Ion channel; Other ion channel; Bcl-2 family; Miscellaneous ion channel
Gene: Protein-coding gene on chromosome 22 (17,628,848 to 17,730,855, forward strand). Ensembl gene ENSG00000099968.
Subcellular location: Mitochondrion membrane (Isoform 2); Nucleus; Nucleus (Isoform 1)
Subcellular location (Human Protein Atlas): Mitochondria
Gene Ontology:
Molecular function: protein binding; cysteine-type endopeptidase activator activity involved in apoptotic process
Biological process: apoptotic process; regulation of apoptotic process
Cellular component: membrane; mitochondrion; mitochondrial membrane; nucleus
Genetic constraint (gnomAD): Loss-of-function variants: 9 observed, 21.29 expected, observed/expected ratio (o/e) 0.42, 90% interval 0.25 to 0.74. The upper end of that interval is the gene's LOEUF score, 0.74, which puts it in group 3 of 6, group 1 being the genes least tolerant of losing a copy. Missense variants: 470 observed, 568.42 expected, observed/expected ratio (o/e) 0.83, 90% interval 0.77 to 0.89. Synonymous variants: 227 observed, 228.13 expected, observed/expected ratio (o/e) 1, 90% interval 0.89 to 1.11.
Homologues: Orthologues: chimpanzee BCL2L13 (93% identical), macaque BCL2L13 (88% identical), dog BCL2L13 (84% identical), rabbit BCL2L13 (81% identical), guinea pig BCL2L13 (80% identical), rat Bcl2l13 (69% identical), mouse Bcl2l13 (68% identical), pig BCL2L13 (65% identical), tropical clawed frog bcl2l13 (49% identical), zebrafish bcl2l13 (42% identical), zebrafish si:ch211-214j24.14 (10% identical).
Diseases named in the same sentence as BCL2L13 in open-access papers:
BCL2L13 is named in the same sentence as 48 diseases in open-access papers, as found by Europe PMC text mining. Sharing a sentence is not in itself a finding about the gene and the disease. The quoted sentences say what the papers report.
glioblastoma (9 papers, 2016 to 2026). The most malignant astrocytic tumor (WHO grade IV). "Interestingly, in a glioblastoma xenograft model, the mitochondria-associated Bcl2-like 13 (Bcl2L13) protein, a member of the Bcl-2 family, was found to promote glioblastoma growth by inhibiting apoptosis through decreasing the ceramide levels in response to chemotherapy treatment." (PMID 38894892, 2024). "Bcl2L13 was shown to be overexpressed in glioblastoma tumors and binds CerS2 and CerS6, which inhibits the de novo synthesis of ceramides." (PMID 38894892, 2024). "For instance, in glioblastoma tumor cells with high expression of BCL2 like 13 (BCL2L13), CERS2 activity is blocked, resulting in the prevention of apoptosis in response to both conventional and targeted therapies." (PMID 37958652, 2023). "For example, BCL2L13 was found elevated in tumors like glioblastoma (GBM) and childhood acute lymphoblastic leukemia (ALL)." (PMID 34193180, 2021). "In glioblastoma, BCL2L13 overexpression inhibits therapy-induced apoptosis." (PMID 39175772, 2024). "IHC performed on primary glioma sections from our Qilu Hospital further confirmed that BCL2L13 was highly expressed in grade II/III astrocytoma and glioblastoma." (PMID 37660127, 2023). "BCL2 like 13 (BCL2L13) targeted DNM1L at the Ser616 site to promote mitochondrial fission and mitophagy, which ultimately enhance the proliferation and invasion of glioblastoma cells." (PMID 39035027, 2024).
acute lymphoblastic leukemia (3 papers, 2021 to 2024). Leukemia with an acute onset, characterized by the presence of lymphoblasts in the bone marrow and the peripheral blood. "High expression of BCL2L13 was also an independent prognostic factor for childhood acute lymphoblastic leukemia." (PMID 38392190, 2024).
Cerebral ischemia (2 papers, 2021). Restriction of arterial blood supply to the brain associated with insufficient oxygenation to support the metabolic requirements of the tissue. "All these results indicate that miR-484 alleviates cerebral ischemia/reperfusion injury-induced neuronal apoptosis in mice by targeting apoptosis facilitator BCL2L13." (PMID 33724167, 2021). "All these results suggested that miR-484 alleviates cerebral ischemia/reperfusion injury-induced neuronal apoptosis in mice by targeting apoptosis facilitator BCL2L13." (PMID 33724167, 2021). "Finally, cerebral infarct size assessment and TUNEL staining confirmed that overexpression of miR-484 alleviated cerebral ischemia/reperfusion injury in mice, and overexpression of BCL2L13 could abolish the effect of miR-484-suppressed cell apoptosis." (PMID 33724167, 2021).
coronary artery disease (2 papers, 2022 to 2024). "Increased miR-96-5p would ameliorate acute myocardial infarction-associated cardiomyocytes injury by targeting BCL2L13, and miR-96-5p may function as a potential diagnostic biomarker for patients with coronary artery disease." (PMID 35485167, 2022).
lung adenocarcinoma (2 papers, 2022 to 2023). A carcinoma that arises from the lung and is characterized by the presence of malignant glandular epithelial cells. "In node-negative breast cancer and lung adenocarcinoma, BCL2L13 is negatively associated with tumor aggressive behaviors, indicating that BCL2L13 plays different roles based on the specific cell type." (PMID 37660127, 2023).
clear cell renal cell carcinoma (1 paper, 2021). "Functional enrichment analysis and hubs of BCL2L13 co-expressed genes in clear cell renal cell carcinoma (ccRCC) and papillary renal cell carcinoma (pRCC) were carried out on Cytoscape." (PMID 34193180, 2021). "Compared to HEK (human embryonic kidney) 293 T cells, the expression of BCL2L13 is much lower in clear cell renal cell carcinoma cell line 786-0, consistent with the silico-based analyses." (PMID 34193180, 2021).
epileptic seizures (1 paper, 2015). "These, together with our findings, suggest that fine-tuning of key components of mitochondrial apoptotic pathways, mediated by miR-124 and miR-137 cooperativity on BCL2L13 and its associated functions, may contribute to the early response to epileptic seizures in the DG." (PMID 26207921, 2015).
gastric cancer (1 paper, 2023). A primary or metastatic malignant neoplasm involving the stomach. "BCL2L13 expression is dramatically increased in proximal gastric cancer compared to distal gastric cancer tissues, which may make it a signature of malignant progression in stomach neoplasms." (PMID 37660127, 2023).
glioma (1 paper, 2023). A benign or malignant brain and spinal cord tumor that arises from glial cells (astrocytes, oligodendrocytes, ependymal cells). "Immunohistochemistry (IHC) data from The Human Protein Atlas revealed that increased BCL2L13 levels were associated with increased glioma grade." (PMID 37660127, 2023). "Western blot was then used to verify BCL2L13 expression levels in different commonly used glioma cell lines." (PMID 37660127, 2023). "This study observed that BCL2L13 expression is higher in glioma than in NBT, according to the data from public databases and our IHC staining results." (PMID 37660127, 2023). "Data derived from the CCLE indicated that glioma cell lines possess a higher expression of BCL2L13 than most cancer cell lines derived from other lineages." (PMID 37660127, 2023). "Our results showed that the expression levels of the BCL2L13 protein were increased in several glioma cells, especially in GBM#P3, which is derived from a primary GBM patients." (PMID 37660127, 2023). "A172, with lower BCL2L13 expression compared with other glioma cells, was chosen for ectopic expression experiments." (PMID 37660127, 2023). "In this study, we confirmed that BCL2L13 is highly expressed in glioma compared to normal brain tissue." (PMID 37660127, 2023). "Moreover, upregulation of BCL2L13 correlated with tumor histological grades in glioma." (PMID 37660127, 2023). "Moreover, the upregulation of BCL2L13 correlated with tumor histological grades in glioma." (PMID 37660127, 2023).
heart failure (1 paper, 2018). Inability of the heart to pump blood at an adequate rate to meet tissue metabolic requirements. "Additional studies are needed to determine how BCL2L13 is regulated in cardiac pathology and whether BCL2L13 can be a possible therapeutic target for the treatment of heart failure." (PMID 29576856, 2018).
hereditary spastic paraplegia (1 paper, 2025). Hereditary spastic paraplegias (HSP) comprise a genetically and clinically heterogeneous group of neurodegenerative disorders characterized by progressive spasticity and hyperreflexia of the lower limbs. "Gene therapy applications demonstrate therapeutic potential in hereditary spastic paraplegia (HSP) models, where ARL6IP1 restoration rescues ER–mitochondria homeostasis through LC3B/BCl2L13 interactions, ameliorating HSP‐associated pathophysiology." (PMID 40584408, 2025).
kidney cancer (1 paper, 2021). Primary or metastatic malignant neoplasm involving the kidney. "Multiple web-based portals were employed to analyze the effect of BCL2L13 in kidney cancer using the data from TCGA database." (PMID 34193180, 2021). "The prognostic value of BCL2L13 in kidney cancer is still unclearly." (PMID 34193180, 2021). "It poses an attractive hypothesis that BCL2L13 may be a promising prognosis marker for kidney cancer." (PMID 34193180, 2021). "Therefore, the correlation between miRNA and BCL2L13 in kidney cancer were analyzed." (PMID 34193180, 2021). "Moreover, low BCL2L13 expression correlates with lessened survival probability of kidney cancer." (PMID 34193180, 2021). "While only weak correlation was uncovered between BCL2L13 and the known kidney cancer related genes, we found that voltage-dependent L-type calcium channel subunit beta-1 (CACNB1) and numb-like protein (NUMBL) are the two BCL2L13 negatively correlated genes." (PMID 34193180, 2021). "Previous studies have shown that BCL2L13 has functional consequence in several tumor types, including ALL and GBM, however, its function in kidney cancer remains as yet unclearly." (PMID 34193180, 2021). "This disadvantageous factor is independent of any well-known kidney cancer related genes, so BCL2L13 can be used as an effective indicator for prognostic evaluation of renal cell carcinoma." (PMID 34193180, 2021).
lung squamous cell carcinomas (1 paper, 2023). "Finally, in The Cancer Genome Atlas (TCGA), co-amplification of BCL2L13, BID, CRKL and MAPK1 was present in 0.5% of reported samples, being > 2% among sarcomas or lung squamous cell carcinomas." (PMID 37443114, 2023).
multiple sclerosis (1 paper, 2025). A progressive autoimmune disorder affecting the central nervous system resulting in demyelination. "Variants in the 3’UTR microRNA binding sites of BCL2L13 have been identified in multiple sclerosis, which may alter BCL2L13 protein expression levels and consequently disrupt key processes such as mitophagy and apoptosis." (PMID 41341510, 2025).
pancreatic carcinomas (1 paper, 2023). "In the Catalogue of Somatic Mutations in Cancer (COSMIC) database; 135/13,389 (1.0%) samples showed co-amplification of BCL2L13, BID, CRKL and MAPK1 and frequencies > 2% were found in ovarian or pancreatic carcinomas." (PMID 37443114, 2023).
rectal cancer (1 paper, 2023). A primary or metastatic malignant neoplasm that affects the rectum. "Moreover, the lack of BCL2L13 is associated with a non-response to preoperative chemoradiotherapy (pCRT) in locally advanced rectal cancer patients, providing a potential strategy to predict pCRT efficacy in rectal cancer patients." (PMID 37660127, 2023).
renal carcinoma (1 paper, 2021). A carcinoma arising from the epithelium of the renal parenchyma or the renal pelvis. "Evaluation of BCL2L13 protein level was accomplished through immunohistochemistry on paraffin embedded renal cancer tissue sections." (PMID 34193180, 2021).
renal cell carcinoma (1 paper, 2021). "The clinical proteomic tumor analysis consortium (CPTAC) was then engaged to analyze the protein expression level of BCL2L13 in renal cell carcinoma." (PMID 34193180, 2021). "DNA methylation of BCL2L13 coding regions was not altered in renal cell carcinoma samples." (PMID 34193180, 2021).
retinal diseases (1 paper, 2022). "Apoptosis is also a characteristic hallmark of retinal diseases, so BBC3 and BCL2L13, RARA were investigated, as well as genes (EFEMP1, CFH) involved in the regulation of methylation sites." (PMID 36078063, 2022).
Stroke (1 paper, 2021). Sudden impairment of blood flow to a part of the brain due to occlusion or rupture of an artery to the brain. "Similarly, miR-874-3p has been shown to protect stroke patients from ischemic neuronal injury by inhibiting the pro-apoptotic factors BMF and BCL2L13." (PMID 34830203, 2021).
tauopathy (1 paper, 2024). Neurodegenerative disorders involving deposition of abnormal tau protein isoforms (tau proteins) in neurons and glial cells in the brain. "The brain deficiency of Bcl2l13 causes reduced mitophagy, while loss of an active p-Bcl2l13 predicts downstream reduction in mitophagy that could contribute to increased mitochondrial damage in tauopathy models and human tauopathies." (PMID 38542311, 2024).
viral infection (1 paper, 2024). "SARS-CoV-2 Nsp14 mediates the effects of viral infection on the host cell transcriptome, with BCL2L13 showing downregulated expression." (PMID 38674024, 2024).
cancer (9 papers, 2011 to 2023). A tumor composed of atypical neoplastic, often pleomorphic cells that invade other tissues. "Of the variant-phenotype associations uncovered by our study, only the association between BCL2L13 and cancer has been previously reported." (PMID 33750777, 2021). "The physiological roles of BCL2L13 include regulation of growth, development, and energy metabolism, while the pathological implications include cancer, cardiovascular disease, and degenerative disease." (PMID 36226317, 2022). "In this study, we profiled BCL2L13 across 33 cancer types in the Cancer Genome Atlas (TCGA), and found that its mRNA expression is significantly reduced in ccRCC and pRCC." (PMID 34193180, 2021). "ccRCC was selected for further mechanism exploration, because of the more significant prognostic role of BCL2L13 low expression in this kind of cancer." (PMID 34193180, 2021). "Moreover, low expression of BCL2L13, which was related to weakened oxidative phosphorylation and enhanced glycolysis, was often found in cancer cells." (PMID 34193180, 2021). "The BCL2L13 gene is involved in a wide range of cancers, but whether BCL2L13-mediated mitophagy affects tumor development is still poorly understood." (PMID 33262988, 2020).
tumor (5 papers, 2017 to 2023). "The results demonstrated that knockdown of BCL2L13 significantly reduced tumor growth (~55 × 108 vs. ~30 × 108 photons/s, sh-NC vs. sh-BCL2L13)." (PMID 37660127, 2023). "BCL2L13 expresses anomalously in a variety of tumors, participating in tumor progression with its apoptosis-regulating activity." (PMID 34193180, 2021). "Positively correlated genes that would decrease and increase apoptotic death of the tumor cells include BCL2L13, and PTEN." (PMID 28400759, 2017). "Finally, to determine whether BCL2L13-induced autophagy protects tumor cells, cell viability, migration, and invasion ability were assessed in the presence of inhibitors of autophagy, 3-MA or Baf, in BCL2L13-overexpressing A172 cells." (PMID 37660127, 2023). "Moreover, the IHC results also indicated a low expression of BCL2L13 in tumor tissues." (PMID 34193180, 2021). "BCL2L13 low expression significantly correlated with poor prognosis in ccRCC (P = 0.0021), which was independent of patients’ gender or tumor grade." (PMID 34193180, 2021). "The poor prognosis of ccRCC that derived from down-regulated BCL2L13 is independent of patients’ gender or tumor grade." (PMID 34193180, 2021). "The BCL2L13 protein expression is consistently lower in ccRCC patients compared to healthy crowd, which is independent of the tumor stage." (PMID 34193180, 2021). "Further analysis in ccRCC and pRCC indicated that the reduced BCL2L13 mRNA is independent of patients’ race, gender, age, lymph node metastasis status, clinical stages and tumor subtypes." (PMID 34193180, 2021). "Specifically, hypermethylation of BCL2L13 promoter in ccRCC is independent of patients’ age, gender, race, clinical stages, lymph node metastasis status and tumor grade." (PMID 34193180, 2021).
infection (3 papers, 2017 to 2023). The state of being infected such as from the introduction of a foreign agent such as serum, vaccine, antigenic substance or organism. "Quantitative real-time PCR (qRT-PCR) and western blot results showed that BCL2L13 levels in U251, GBM#P3, and GBM#BG5 cells were significantly decreased after infection lentiviruses encoding one of three BCL2L13, especially the case of sh-BCL2L13#2 and #3." (PMID 37660127, 2023).
metabolic disease (1 paper, 2023). A congenital disorder (due to inherited enzyme abnormality) or acquired (due to failure of a metabolically important organ) disorder resulting from an abnormal metabolic process. "On this basis, a more in‐depth investigation of the specific mechanisms of FKBP8 and BCL2L13‐related mitophagy pathways in MS‐related metabolic diseases such as IR and T2DM can help to understand the role of mitophagy in MS more comprehensively and thorough." (PMID 37039609, 2023).
BCL2L13 also shares sentences with these, for which no sentence is quoted: bacterial infection (2 papers); cat-eye syndrome (2); Legionella infection (2); acute myeloblastic leukemia (1); acute myocardial infarction (1); astrocytoma (1); breast carcinoma (1); cardiovascular disease (1); cervical cancer (1); chronic obstructive pulmonary disease (1); co-infection (1); degenerative disease (1); Hyperglycemia (1); leukemia (1); melanoma (1); motor neuron degeneration (1); papillary renal cell carcinoma (1); prostate carcinoma (1); sarcoma (1); sarcopenia (1); tubular aggregate myopathy (1); type 2 diabetes mellitus (1).